FNTB (farnesyltransferase, CAAX box, subunit beta)
Description:
Essential subunit of the farnesyltransferase complex. Catalyzes the transfer of a farnesyl moiety from farnesyl diphosphate to a cysteine at the fourth position from the C-terminus of several proteins having the C-terminal sequence Cys-aliphatic-aliphatic-X.
Synonyms: FPTB
Tractability: Small molecule: an approved drug acts on it; a structure with a bound ligand is known; a high-quality ligand is known; it belongs to a druggable protein family. PROTAC: ubiquitination databases record sites on it; its protein half-life has been measured; a small molecule that binds it is known.
Target class: Enzyme; Transferase
Chemical probes: A-409100 (high quality), L-778123, LONAFARNIB, PD080947, PD080969, PD081101, PD081277, PD081432, PD081466, PD081699, PD081831, PD081931, PD081951, PD081977, PD082279, PD082404, PD082504, PD082636, PD082656, PD082821, and 12 more
Gene: Protein-coding gene on chromosome 14 (64,986,837 to 65,062,655, forward strand). Ensembl gene ENSG00000257365.
Subcellular location (Human Protein Atlas): Centrosome
Pathways (Reactome):
Disease: Potential therapeutics for SARS
Immune System: GBP-mediated host defense
Sensory Perception: Inactivation, recovery and regulation of the phototransduction cascade
Signal Transduction: RAS processing
Gene Ontology:
Molecular function: acetyltransferase activator activity; enzyme binding; protein binding; protein farnesyltransferase activity; zinc ion binding; catalytic activity; peptide binding; prenyltransferase activity; protein prenyltransferase activity
Biological process: protein farnesylation; regulation of microtubule-based movement; positive regulation of cell cycle; positive regulation of cell population proliferation
Cellular component: microtubule associated complex; protein farnesyltransferase complex; cytosol
Genetic constraint (gnomAD): Loss-of-function variants: 29 observed, 59.46 expected, observed/expected ratio (o/e) 0.49, 90% interval 0.36 to 0.67. The upper end of that interval is the gene's LOEUF score, 0.67, which puts it in group 2 of 6, group 1 being the genes least tolerant of losing a copy. Missense variants: 449 observed, 557.35 expected, observed/expected ratio (o/e) 0.81, 90% interval 0.75 to 0.87. Synonymous variants: 230 observed, 223.94 expected, observed/expected ratio (o/e) 1.03, 90% interval 0.92 to 1.15.
Homologues: Orthologues: chimpanzee FNTB (100% identical), pig FNTB (97% identical), rat Fntb (97% identical), dog FNTB (96% identical), macaque FNTB (92% identical), mouse Fntb (88% identical), guinea pig FNTB (85% identical), tropical clawed frog fntb (70% identical), zebrafish fntb (67% identical), Drosophila melanogaster Fntb (47% identical), Caenorhabditis elegans fntb-1 (42% identical). Paralogues in human: RABGGTB (23% identical), PGGT1B (23% identical).
Diseases named in the same sentence as FNTB in open-access papers:
FNTB is named in the same sentence as 12 diseases in open-access papers, as found by Europe PMC text mining. Sharing a sentence is not in itself a finding about the gene and the disease. The quoted sentences say what the papers report.
breast carcinoma (2 papers, 2022 to 2024). "Previous research on breast cancer indicated that FNTB promoter polymorphisms were independent prognostic biomarkers, particularly in patients with early TNBC." (PMID 39148981, 2024). "We, for first time, analysed clinical relevance of FNTB promoter polymorphisms in breast cancer patients and demonstrated the independent prognostic relevance of FNTB-173 6G > 5G and FNTB-609 G/C." (PMID 35158735, 2022). "The objective of this study was to explore the clinical relevance of farnesyltransferase β-subunit (FNTB) single nucleotide promoter polymorphisms (FNTB-173 6G > 5G (rs3215788), -609 G > C (rs11623866) and -179 T > A (rs192403314)) in early breast cancer." (PMID 35158735, 2022). "Taken together, we describe for the first time, a link between FNTB promoter polymorphism and the prognosis of breast cancer patients." (PMID 35158735, 2022). "Taking all our findings together, we describe, for the first time, a link between FNTB promoter polymorphisms and breast cancer prognoses." (PMID 35158735, 2022). "Conclusively, we report, for the first time, a link between FNTB promoter polymorphisms, particularly FNTB-609 G > C, and PR status in breast cancer patients." (PMID 35158735, 2022). "Since we observed the association of FNTB promoter polymorphisms with PR status (refer to Section 3.1), we re-performed the univariate Cox regression analysis after stratifying the patients according to the intrinsic subtypes of breast cancer." (PMID 35158735, 2022). "Therefore, this study focussed on the clinical relevance of polymorphisms in FNTB, the gene encoding the catalytically active β-subunit of farnesyltransferase, in early breast cancer." (PMID 35158735, 2022). "Nevertheless, since the mechanistic background of farnesyltransferase signalling was beyond the scope of our present study, further in vitro experiments will be warranted in order to decode FNTB-associated signalling networks and their contribution to the malignant progression of breast cancer." (PMID 35158735, 2022). "Finally, we used electrophoretic mobility shift assays (EMSAs) to confirm in vitro that the polymorphism FNTB-173 6G > 5G resulted in the differential binding of nuclear proteins from five different breast cancer cell lines." (PMID 35158735, 2022). "Here again, we suppose that, in particular, the homozygous FNTB-173 6G/6G genotype is associated with increased farnesyltransferase activity, a more active RAS signalling pathway and an aggressive breast cancer phenotype with poor outcome." (PMID 35158735, 2022). "The germline genetic variability of the FNTB locus and its clinical relevance for breast cancer is still an open question, particularly since promising preclinical data on FTIs are in contrast to the mostly unsuccessful clinical trials." (PMID 35158735, 2022). "This is the first study on breast cancer suggesting that FNTB promoter polymorphisms are independent prognostic biomarkers, particularly in patients with early triple negative breast cancer (TNBC), and possibly modulate FNTB transcriptional activity." (PMID 35158735, 2022). "However, the functional and clinical relevance of FNTB’s genetic variability in the context of breast cancer is completely unknown." (PMID 35158735, 2022). "This is the first study on breast cancer suggesting that FNTB promoter polymorphisms (i) are independent prognostic biomarkers, particularly in patients with early TNBC, and (ii) could modulate FNTB’s transcriptional activity." (PMID 35158735, 2022). "Therefore, we suggest that the -609 C/C genotype promotes FNTB transcriptional activity, RAS farnesylation and RAS signalling, which, in turn, may contribute to a more aggressive breast cancer phenotype with a high risk of relapse and poor prognosis." (PMID 35158735, 2022).
breast carcinoma (continued). "From the clinical translational point of view, our data strongly suggest that FNTB promoter polymorphisms could be useful for independent prognostic stratification in primary non-metastasized breast cancer patients in order to identify patients with a high risk of recurrence and poor prognosis." (PMID 35158735, 2022). "The absent prognostic relevance of FNTB polymorphisms in hormone receptor-positive breast cancer patients could possibly be explained by the fact that RAS signalling, for which the activity of farnesyltransferase is rate-limiting, has a rather subordinate role in this type of breast cancer." (PMID 35158735, 2022). "However, further in vitro experiments, which were beyond the scope of the present translational study, will be needed in order to confirm the putative role of GLIS3 and ZNF658 in FNTB’s transcriptional regulation and its effects on oncogenic RAS signalling in breast cancer." (PMID 35158735, 2022).
ovarian carcinoma (2 papers, 2022 to 2024). A malignant neoplasm originating from the surface ovarian epithelium. "Among them, FNTA, HSPA5, NEU1, CCND1, CASP1, CASP3 had a negative causal association with ovarian cancer development, and HMGCR, PLA2G4A, ITGAL, PTGS1, FNTB had a positive causal association with ovarian cancer development." (PMID 38651149, 2024). "By screening 31 drugs with 110 targets, FNTA, HSPA5, NEU1, CCND1, CASP1, CASP3 were negatively correlated with ovarian cancer, and HMGCR, PLA2G4A, ITGAL, PTGS1, FNTB were positively correlated with ovarian cancer." (PMID 38651149, 2024). "The functionality of the FNTB-609 G/C promoter has already been proposed by us in a previous study on ovarian cancer, in which we experimentally demonstrated, by reporter assays, that the -609 G allele is associated with increased FNTB transcription." (PMID 35158735, 2022).
triple-negative breast carcinoma (2 papers, 2022 to 2024). An invasive breast carcinoma which is negative for expression of estrogen receptor (ER), progesterone receptor (PR), and human epidermal growth factor receptor 2 (HER2). "The polymorphisms in FNTB promoters are independent predictors of survival in patients with triple-negative breast cancer." (PMID 38672293, 2024).
aortic coarctation (1 paper, 2020). "Previous studies of our team have shown that the tissue of the heart in the suprarenal abdominal aortic coarctation (AAC) group showed overexpression of farnesyltransferase‐beta (FNTB) and the activation of the downstream protein Ras was enhanced." (PMID 32579303, 2020).
cardiac hypertrophy (1 paper, 2020). "Our data provide a new evidence that cardiomyocyte‐specific overexpression of FNTB could contribute to cardiac hypertrophy and death of cardiomyocytes in myocardial remodelling." (PMID 32579303, 2020).
hepatocellular carcinoma (1 paper, 2026). A malignant tumor that arises from hepatocytes. "Gene expression analysis of FNTB in liver hepatocellular carcinoma (HCC) samples demonstrated significantly higher expression in tumor tissues compared to normal tissues (p<0.05), indicating its potential relevance in cancer progression." (PMID 41346770, 2026).
melanoma (1 paper, 2025). A malignant, usually aggressive tumor composed of atypical, neoplastic melanocytes. "Evaluation of FNTB levels as well as NRAS mutation status could provide potentially treatment-predictive information that could guide the design of future clinical trials including tipifarnib or other FTIs in melanoma." (PMID 39995872, 2025). "Further, evaluation of FNTB levels across different cancer CL types indicated that skin/melanoma cells commonly express high levels of FNTB." (PMID 39995872, 2025).
schizophrenia (1 paper, 2020). A major psychotic disorder characterized by abnormalities in the perception or expression of reality. "Accordingly, we assayed protein expression of the prenyltransferases subunits FNTA, FNTB, PGGT1B, RABGGTA, and RABGGTB in DLPFC from schizophrenia and matched comparison subjects." (PMID 32066669, 2020). "To test this, we assayed protein expression of the five prenyltransferase subunits (FNTA, FNTB, PGGT1B, RABGGTA, and RABGGTB) in postmortem dorsolateral prefrontal cortex from patients with schizophrenia and paired comparison subjects (n = 13 pairs)." (PMID 32066669, 2020).
cancer (5 papers, 2018 to 2026). A tumor composed of atypical neoplastic, often pleomorphic cells that invade other tissues. "Interestingly, FNTB expression was positively correlated with pro-tumor immune cells, including macrophages, neutrophils, regulatory T cells, myeloid-derived suppressor cells (MDSCs), and cancer-associated fibroblasts (CAFs)." (PMID 41346770, 2026). "FTase proteins (FNTA and FNTB) as well as eight of the 116 PFPs are known cancer-relevant proteins as per COSMIC Cancer Gene Census49 or TCGA50 (KRAS, HRAS, NRAS, RHEB, RHOA, DDX3X, ARID2, and SAV1)." (PMID 39995872, 2025).
tumor (2 papers, 2022 to 2026). "Analysis of the farnesyltransferase (FNTB) gene revealed significantly higher expression in cancerous tissues and a positive correlation with pro-tumor immune cell infiltration." (PMID 41346770, 2026). "Furthermore, FNTB may exert further unknown tumour-promoting functions in TNBC that relate to the biology of tumour stem cells." (PMID 35158735, 2022).
FNTB also shares sentences with these, for which no sentence is quoted: lung adenocarcinoma (1 paper); osteosarcoma (1).